CCL4 (C-C motif chemokine ligand 4)
Diseases named in the same sentence as CCL4 in open-access papers (continued):
Sharing a sentence is not in itself a finding about the gene and the disease.
liver fibrosis (continued). "Overall, FZHY could alleviated CCL4- induced liver fibrosis." (PMID 37161575, 2023). "Finally, in the CCL4-induced rat hepatic fibrosis model, the YJSB drug group activated the Keap1-Nrf2 signaling pathway, resulting in Keap1 release in the cytoplasm and Nrf2 entry into the nucleus to initiate a series of antioxidant reactions and promote the generation of antioxidant proteins." (PMID 37229248, 2023). "Similarly, genetic ablation of p21 also prevents liver fibrosis induced by CCL4." (PMID 36890528, 2023). "Similarly, the gene coding for the ECM modifying enzyme MMP2 and tissue inhibitor of MMPs-2 (Mmp2, Timp2), which respectively exert anti- and pro-fibrogenic roles in liver fibrosis, were strongly upregulated by CCL4 treatment in both Nlrc5-/- and control mice livers." (PMID 34712238, 2021). "Macrophage-specific deletion of Atg5 could aggravate CCL4-induced liver fibrosis." (PMID 31614437, 2019). "Previous studies demonstrated that blocking the CB1 receptor by pharmacological antagonistslike RIM (SR141716A) or genetic inactivation like in Cnr1-/- mice limited theprogression of hepatic fibrosis whether the fibrosis was induced by bile ductligation, CCL4 or thioacetamide." (PMID 31389521, 2019). "Moreover, a recent study showed that Periplaneta americana extracts alleviated CCL4-induced hepatic fibrosis in rats via the inhibition of TGF-β1, nuclear factor kappa B (NF-κB), alpha-smooth muscle actin (α-SMA), and tissue inhibitor of metalloproteinases 1 (TIMP-1)." (PMID 31885648, 2019). "Besides, CCL4-induced early and established liver fibrosis mice was brought into our experiment." (PMID 21629648, 2011). "In a Ccl4-induced hepatic fibrosis murine model, specific knockout of MED23 in stem cells resulted in exacerbated liver fibrosis, accompanied by increased chemokine production and inflammatory infiltration." (PMID 40940746, 2025). "In conclusion, our study indicates that Huangqi Decoction exerts a hepatoprotective effect against CCL4-induced injury, promotes autophagy, and suppresses apoptosis through the PI3K/Akt/mTOR signaling pathway in hepatic fibrosis rats." (PMID 39388703, 2025). "Our results confirm that Notch signaling pathway is activated in both CCL4 and DDC model of liver fibrosis and that αSMA positive myofibroblasts are of activated hepatic stellate cells origin." (PMID 39529885, 2024). "Animal experimental studies have demonstrated that thrombocytopenia can further aggravate liver fibrosis induced by BDL and CCL4 in mice." (PMID 39635524, 2024). "In a CCL4 mouse model of fibrosis, GATA overexpression in HSCs was shown to promote liver fibrosis regression." (PMID 39201329, 2024). "In pre-clinical models of hepatic fibrosis, GDNF has been found to have varied effects, inducing cirrhosis in CCL4 and bile duct ligation models but protecting against hepatic fibrosis in a high-fat-diet-fed model." (PMID 38339124, 2024). "In CCL4-induced liver fibrosis, small p97/vcp-interacting protein (SVIP) activated autophagy and alleviated liver fibrosis." (PMID 38393131, 2024). "A model of CCL4-induced liver fibrosis was developed, and the effects of FZHY on liver fibrosis were investigated." (PMID 37161575, 2023). "The livers from WT mice were more fibrotic than those from ANGPTL8-KO mice, and CCL4 upregulated the expression of ANGPTL8 in mouse livers, suggesting that ANGPTL8 promotes the progression of CCL4-induced liver fibrosis." (PMID 37188659, 2023). "In contrast to the CCL4-induced liver fibrotic model in vivo, lipopolysaccharide (LPS), allyl alcohol, and TGF-β1 were commonly adopted for hepatic fibrosis in vitro." (PMID 37798761, 2023). "Among these hub genes, some are cytokines and chemokines closely related to liver fibrosis (IFNG, CCL3, CCL4, CCL5, and CXCR4)." (PMID 35903097, 2022).
liver fibrosis (continued). "We further analyzed the markers of liver fibrosis, collagen-1, and CTGF are also important marker of liver fibrosis, and their expression levels were significantly increased in CCL4 group." (PMID 36524217, 2022). "Given that hepatic stellate cells play central roles in liver fibrosis, the intensified deposition of SMA in Hpa-tg liver upon CCL4 stimulation suggests a higher activity of hepatic stellates." (PMID 35805119, 2022). "Next, the changes in serum levels of liver fibrosis markers (HA, PIIINP, LN, and CIV) were determined; we found that the serum levels of HA, PIIINP, LN, and CIV in the CCL4-treated group were significantly increased." (PMID 36524217, 2022). "Recently, administering LNA-anti-miR-132 in mice has been shown to attenuate CCL4-induced inflammatory mediators IL-1β and COX2 to alleviate liver fibrosis." (PMID 35163786, 2022). "For this, we first established a CCL4-induced liver fibrosis model and found that HBO1 knockdown exhibited a better therapeutic effect on CCL4-induced liver fibrosis." (PMID 36524217, 2022). "Autophagic degradation of Cav-1 and F-actin remodeling were increased in CCL4-induced LSEC defenestration and liver fibrosis by inhibiting the NO-dependent PI3K-Akt-mTOR pathway." (PMID 32724454, 2020). "The current report now shows that CDH11 expression is also increased in fibrotic livers of mice treated with CCL4 and CDH11 modulates the development of liver fibrosis." (PMID 31269038, 2019). "In the present study we aim to translate the widely used CCL4 and TAA mouse models for liver fibrosis to zebrafish embryos in order to obtain a new model which is suitable for high throughput studies and show its applicability to study therapeutic effects." (PMID 30375438, 2018). "Hepatic fibrosis models were developed in mice by induction with BDL (n = 15) (sham‐operated as control group, n = 10) or CCL4 (n = 15) (olive oil as control group, n = 10)." (PMID 28766848, 2017). "The reversibility of NASH in the CCL4 and BDL models suggests that hepatic fibrosis is reversible upon removal of the factor(s) stimulating the development and progression of NASH." (PMID 26761430, 2016). "To study the regulatory function of acetylation in liver inflammation and fibrosis in largemouth bass, we initially established fish models with acute liver inflammation induced by LPS and liver fibrosis mediated by a high-carbohydrate and high-fat diet (HCHFD) or CCL4 administration." (PMID 41322258, 2025). "Administration of VA + NPs and BTZ + NP to the CCL4-liver fibrosis-induced mice showed no great potential for altering either NF-κB or TGF-β expression level." (PMID 40636301, 2025). "Additionally, we verified the upregulation of these genes in liver fibrosis in the BDL- and CCL4-induced mouse models." (PMID 39194690, 2024). "For example, adenoviral overexpression of FoxO1 in wild-type mice promoted liver fibrosis and hepatic stellate cell activation induced by CCL4 injection, whereas this effect was blocked in mice lacking liver-specific TGF-β1." (PMID 39382800, 2024). "It has been demonstrated that B cells knockout mice given CCL4 injections had significantly lower hepatic fibrosis than normal control mice, suggesting that B cells have a pro-fibrotic effect and this effect is independent of antibodies and T cells." (PMID 36875101, 2023). "Our results show that in aged mice, significant liver fibrosis can develop after 21 weeks of induction, a phenomenon that has been difficult to achieve in previous animal models without the addition of CCL4 induction." (PMID 37228085, 2023). "This may reveal that hypoxia generated by the metabolism of ethanol may increase the expression of HIF-1α in hepatic cells after subjecting to CCL4, prompting HIF-1α to play a significant role in liver fibrosis progression." (PMID 36523459, 2022).
liver fibrosis (continued). "Sirius red and Masson staining further showed that the application of GW4869 significantly inhibited the therapeutics effects of MSCs on CCL4-induced liver fibrosis; as a result, the transplanted MSCs failed to improve collagen deposition." (PMID 35858897, 2022). "Hypoxia has been shown to be an important inducing factor of inflammation and fibrosis in chronic liver disease; HIF-1a is a key transcription factor for liver fibrosis and is involved in the biliary ligation (BDL) and carbon tetrachloride- (CCL4-) induced liver fibrosis in rats." (PMID 33880382, 2021). "Both 3-MA, a chemical inhibitor of autophagy, and transfection with siRNAs targeting Atg3 and Atg7 inhibited autophagy in HSCs and in the livers of CCL4- or TAA-treated mice and reduced lipid metabolism and energy production, which then inhibited ECM production and liver fibrosis." (PMID 32724454, 2020). "To investigate whether TIM‐4 expression is influenced by liver fibrosis, we measured the expression of hepatic TIM‐4 in CCL4‐induced liver injury mice." (PMID 31755616, 2020). "Despite the evidence on the role of miR-21 and fibrosis, a recent study found that antisense inhibition or genetic deletion of miR-21 does not alter HSC activation or liver fibrosis in CCL4 induced liver fibrosis mice models." (PMID 32083086, 2020). "Impaired autophagy by deletion of Atg7 in endothelial cells did not affect liver homeostasis but amplified liver fibrosis without increasing liver injury following CCL4-treatment." (PMID 31614437, 2019). "The beneficial effects of RSV treatment have also been reported to improve liver fibrosis induced by CCL4 in mice and in mice and adult humans with non-alcoholic fatty liver disease." (PMID 31717714, 2019). "For instance, experiment shows that Sal B may induce liver fibrosis in rats by down-regulating CD14 expression and blocking endotoxin signaling to antagonize CCL4." (PMID 30842735, 2019). "Altogether this indicates that CCL4 yolk sac injections do not lead to liver fibrosis in zebrafish embryos." (PMID 30375438, 2018). "TLR4 signaling in HSCs, but not in Kupffer cells, is crucial for the development of liver fibrosis induced by alcohol, CCL4, and viral infection." (PMID 29321784, 2017). "In the present study we report that activation of GPBAR1 in mice administered CCL4, failed to attenuate liver fibrosis, but protected against development of portal hypertension." (PMID 26539823, 2015). "Moreover, CCR1 and CCR5, receptors for the chemokines CCL3/MIP1α, CCL4/MIP1β and CCL5/RANTES, were found to promote liver fibrosis in mice." (PMID 23259611, 2012). "In order to identify changes in the miRNA expression profile between advanced liver fibrosis and non-fibrotic liver, we intra-peritoneally administered CCL4 in olive oil or olive oil alone twice a week for 4 weeks and then once a week for the next 4 weeks." (PMID 21283674, 2011). "Moreover, CCR1 and CCR5, receptors for the chemokines CCL3/MIP1α, CCL4/MIP1β and CCL5/RANTES, promote liver fibrosis in mice." (PMID 20548789, 2010). "This study was performed in a CCL4-induced liver fibrosis mouse model, which might not reflect all types of liver fibrosis." (PMID 39354960, 2022). "Clinical studies have also confirmed that LWWL also has definite therapeutic effects on liver fibrosis, we also demonstrated that LWWL could attenuate hepatic fibrosis via modulation of TGF-β1 and NF-κB signaling pathways in BDL and CCL4-induced hepatic fibrosis rat models." (PMID 34149411, 2021). "Our studies based on chronic CCL4, bile duct ligation, and subacute TAA mouse models show that SYK in monocyte-derived macrophages (MoMFs) is fully dependent on phosphorylation of Erk to up-regulate the expression of Hif1α, thereby forming the crosstalk with SYK to drive liver fibrosis progress." (PMID 34853322, 2021).
liver fibrosis (continued). "In vivo results showed that CCL4 treatment could increase the expression of TGF-β1, TβR-I, Smad 2, and Smad 3 in liver tissue and inhibit the expression of Smad 7, thereby reducing the formation of liver fibrosis." (PMID 29853950, 2018). "In the CCL4-induced rat liver fibrosis model, infection with the recombinant lentiviral expression vector carrying the rat PPAR-γ gene resulted in suppressing hepatic stellate cell (HSC) proliferation and hepatic fibrosis and inhibiting the expression of α-SMA and type I collagen." (PMID 30116754, 2018). "However, in our studies, Rspo1 injections did not facilitate liver fibrosis in vivo with or without CCL4 damage (and data not shown)." (PMID 29079780, 2017). "Importantly, administration of LNA-modified miR-142-5p ASO and miR-130a-3p mimic failed to inhibit CCL4-induced liver fibrosis in Ccr2−/− mice." (PMID 26436920, 2015). "The enhanced expression of miR-199a-5p was confirmed in two independent experimental models of liver fibrosis and was correlated with the severity of liver fibrosis, as BALB/C mice have a more pronounced liver fibrosis than C57BL/6 mice, following administration of CCL4." (PMID 23459460, 2013). "However, it is important to note that the CCL4 model has its limitations and may not fully recapitulate the complexity of human liver fibrosis." (PMID 39388703, 2025). "Chrebpα‐LKO mice are highly sensitive to both chemical (CCL4 and TAA) and bile duct ligation (BDL)‐induced liver injury and developed more advanced liver fibrosis without affecting liver lipid content." (PMID 40548862, 2025).
COVID-19 (121 papers, 2020 to 2025). A disease caused by infection with severe acute respiratory syndrome coronavirus 2. "Similar to CCL-2, CCL-4 was also reported to be elevated in COVID-19 patients and correlated to several variants." (PMID 38646483, 2024). "Six hub genes (FCGR3A, CD69, IFNG, CCR7, CCL5, and CCL4) were closely associated with COVID-19 and HF." (PMID 36420258, 2022). "In fact, IL15 is part of an immune-based biomarker signature associated with mortality in COVID-19 patients, and CCL4 has been shown to be elevated in COVID-19 patients who eventually died due to the disease." (PMID 34071557, 2021). "Of the significantly dysregulated cytokines in both COVID-19 and CAD, pro-inflammatory cytokines CCL3 and CCL4 have been associated with COVID-19 severity." (PMID 34071557, 2021). "Macrophage inflammatory protein-1β (MIP1b; more commonly known as Chemokine (C-C motif) ligands 4 (CCL4) was inversely associated with COVID-19 [odds ratio (OR) 0.97 per SD, 95% confidence interval (CI) 0.96–0.99] but not after adjustment for multiple comparisons." (PMID 34163532, 2021). "Severe COVID-19 patients over-expressed CCL4, and lung macrophages showed an over-expression of the gene." (PMID 38543303, 2024). "In fact, when compared to controls, amniotic fluid from COVID-19-affected pregnancies demonstrated elevated levels of several pro-inflammatory cytokines, including IL-12 p40, CCL4, CCL7, CCL13, TNF, IL-1a, IL-17A, and IL-17E." (PMID 39390219, 2024). "Mild COVID-19 cases were characterized by a unique biosignature comprising C-C Motif Chemokine Ligand 4 (CCL4), and Interferon Regulatory Factor 1 (IRF1)." (PMID 39040605, 2024). "The increased presence of chemokines CCL2, CCL4, CXCL8, and CXCL10 in the plasma was observed among the Wuhan, Alpha, Delta, and Omicron variants of moderate to severe COVID-19 patients when compared to healthy individuals." (PMID 37632046, 2023). "A high concentration of CCL4 has been identified in secretions of patients with severe COVID-19, although its expression has also been found in dengue-infected dendrites, promoting vasodilatation and endothelial dysfunction in both diseases." (PMID 37580025, 2023). "We also examined the expression of previously reported inflammatory cytokines (TNF, IL6, IL1B, CCL3, CCL4 or CXCL2) produced by circulating monocytes in patients with COVID-19." (PMID 37363730, 2023). "In a study on COVID-19, CCL4 was highly expressed in the bronchoalveolar lavage fluid of patients, and CCL5 expression was variable." (PMID 36420258, 2022). "In another study, CCL4 expression levels were lower in patients with COVID-19, particularly in severely ill patients." (PMID 36420258, 2022). "The activated and effector status of NK cells has been also confirmed in BALF as GZMB, GZMA, PRF1, HAVCR2 (Tim-3), and CCL4 are upregulated in COVID-19 patients compared to controls." (PMID 35844604, 2022). "On the other hand, lower circulating levels of IL-6, TNF-α, IL-α, and CCL4 were observed in the asymptomatic group of pregnant women with COVID-19 than healthy pregnant women." (PMID 36016660, 2022). "Further studies are warranted to determine surface IDE levels in different subsets of disease-related classical monocytes and its relevance in regulating CCL3 and CCL4 levels in COVID-19 patients." (PMID 36232381, 2022). "In our cohorts, the levels of MIP chemokines CCL3/MIP-1α and CCL4/MIP-1β, although exceeding the numbers found in the healthy donors’ cohort, varied depending on the COVID-19 severity and virus genetic variant." (PMID 36012323, 2022). "Recently, it has been reported that CCL3 and CCL4 are significantly upregulated at later stages of the disease in patients with severe COVID-19." (PMID 36232381, 2022). "Serological TNF-α, IL-6, CCL4 and IL-4 levels were higher in P-COVID-19+ than in P-COVID-19-, although TNF-α was significantly higher in P-COVID-19+ than in P-COVID-19-." (PMID 35901034, 2022).